GAPDH (glyceraldehyde-3-phosphate dehydrogenase)
Diseases named in the same sentence as GAPDH in open-access papers (continued):
Sharing a sentence is not in itself a finding about the gene and the disease.
neurodegenerative disease (38 papers, 2011 to 2025). A disorder of the central nervous system characterized by gradual and progressive loss of neural tissue and neurologic function. "Other observed effects included increased autophagy, mitochondrial dysfunction, changes in nuclear staining, and the activation of the GAPDH/Ac-Tau signaling pathway, linked to neurodegenerative diseases." (PMID 40407539, 2025). "The low−temperature stability of the H2O2−oxidized subunit conformer provides an operable framework to study mechanisms associated with gain−of−function activities of oxidized GAPDH to identify novel targets for the treatment of neurodegenerative diseases." (PMID 35562998, 2022). "The dysregulation of GAPDH during oxidative stress has been associated with human pathologies, including neurodegenerative diseases (AD, PD and HD), and metabolic disorders, among others." (PMID 33339386, 2020). "GAPDH interacts with other proteins implicated in the pathogenesis of a variety of neurodegenerative diseases." (PMID 26268247, 2015). "This is significant, because GAPDH and its subcellular trafficking are of particular importance to human metabolism and the pathologies associated with neurodegenerative diseases." (PMID 22028962, 2012). "Similarly, increased CSF content of glyceraldehyde-3-phosphate dehydrogenase is linked with the death of neurons in degenerative disease." (PMID 38600510, 2024). "Moreover, GAPDH is recognized as a major component of amyloid plaques in Alzheimer’s diseased brains and it has been also reported to interact with neurodegenerative disease-associated proteins including the amyloid-β protein precursor (AβPP)." (PMID 31027346, 2019). "Studies demonstrate the functional role of glyceraldehyde-3-phosphate dehydrogenase in the progression of neurodegenerative disease, as impaired glycolytic function and increased pro-apoptotic function is observed in AD and HD, respectively." (PMID 41154162, 2025). "Our data provides a molecular rationale for how oxidative stress elevates S-glutathionylated GAPDH in neurodegenerative diseases and implicates novel targets for therapeutic intervention." (PMID 36982600, 2023). "Under oxidative conditions, oxidized GAPDH is translocated to the nucleus to form aggregates, which act as a seed to accelerate amyloidogenesis, resulting in apoptosis and neurodegenerative diseases." (PMID 35020602, 2022). "Very little is known regarding how these modifications induce and modulate the structure of the signaling conformer and initiate proapoptotic functions of oxidized GAPDH directly involved in the pathophysiology of neurodegenerative diseases." (PMID 35562998, 2022). "This phenomenon occurs in neurodegenerative diseases when GAPDH is overexpressed with a simultaneous decrease in glycolytic activity of the enzyme." (PMID 35448030, 2022). "For instance, under oxidative conditions, GAPDH is oxidized and translocated to the nucleus to form aggregates, which act as a seed to accelerate amyloidogenesis, resulting in neurodegenerative diseases, including Alzheimer's and Parkinson’s diseases." (PMID 35020602, 2022). "Specifically, glyceraldehyde-3-phosphate dehydrogenase (GAPDH) has been shown to interact with neurodegenerative disease-related proteins including β-amyloid precursor protein (AβPP)." (PMID 33926067, 2021). "In agreement with our results,GAPDH has stable expression in the human brain, particularly the cerebellum, in patients with various neurodegenerative diseases as well as in normal control patients (Coulsonet al., 2008;Grunblattet al., 2004)." (PMID 37942409, 2021). "Remarkably, neuroprotective actions of several anti-apoptotic drugs involve the blockade of the GAPDH/Siah1 system and inhibit GAPDH aggregation to reduce the effects of neurodegenerative diseases." (PMID 31027346, 2019). "GAPDH likely plays a role in neurodegenerative diseases via a cell death cascade that involves GAPDH, nitric oxide, and the E3 ubiquitin ligase Siah." (PMID 28335774, 2017).
neurodegenerative disease (continued). "In addition, GAPDH has been suggested to have high affinity for AD-associated proteins, including β-amyloid, β-amyloid precursor protein, and tau, and to be involved in the NO/GAPDH/Siah-1 apoptotic cell death cascade, particularly in neuronal cell death associated with neurodegenerative diseases." (PMID 28251161, 2017). "Such proteins that are degraded via CMA include those associated with neurodegenerative diseases such as MEF2D, Htt as well as the glycolytic enzyme GAPDH." (PMID 25637286, 2015). "Since GAPDH is an established target of oxidative damage in several neurodegenerative diseases, it is possible that its oxidant-dependent change in nuclear transport and the subsequent increase in cell death are common to multiple forms of neurodegeneration." (PMID 22028962, 2012). "Several proteomic approaches have shown that, as well as heart and skeletal muscle, the brain contains a high content of nitrated proteins in aging and in various neurodegenerative diseases, such as Tau protein, α-synuclein and glyceraldehyde 3-phosphate dehydrogenase." (PMID 34455147, 2021). "Another key enzyme that has raised great interest in the past three decades regarding its role in neurodegenerative disease is GAPDH, a classic glycolytic enzyme that is primarily considered as the “housekeeping” protein and predominantly presents in the cytosol." (PMID 33994936, 2021). "GAPDH has also been discussed in various neurodegenerative diseases." (PMID 32272779, 2020). "Thus, pharmacological regulation of thefunction of three proteins, GAPDH, tTG, and Hsp70, can affect the pathogenesisof two significant neurodegenerative diseases." (PMID 23819039, 2013). "The functionality of HSPA8 and GAPDH in modulating the cellular toxicity of expanded polyQ HTT has been well studied, and SNAP25 has been investigated in the context of neurodegenerative diseases." (PMID 35932982, 2022). "We firstly confirmed that the expression of GAPDH in each sample is equally expressed in both SMA mice and controls since several housekeeping genes have been found to be differentially expressed in some neurodegenerative diseases in some circumstances at protein level." (PMID 27331400, 2016). "These new insights complement the extensive information available regarding GAPDH aggregation and modifications by non-radical and electrophilic post-translational mechanisms that are involved in cell death during the pathogenesis of neurodegenerative diseases." (PMID 39449960, 2015).
bacterial infection (12 papers, 2011 to 2025). "We also discovered that DRAM1 is co-expressed with GAPDH, a gene encoding a key enzyme in the glycolytic pathway that regulates autophagy in response to bacterial infection." (PMID 37919720, 2023). "In bacteria, the glyceraldehyde-3-phosphate dehydrogenase (GAPDH), a crucial enzyme in glycolysis, can be expressed on the outer membrane to play an important role in the bacterial infection process." (PMID 31963816, 2020). "In mice, abundance of systemic acetate in response to bacterial infections was linked to an optimal function of memory CD8 T cells through an enhanced glycolytic rate and acetylation of glyceraldehyde 3-phosphate dehydrogenase (GAPDH)." (PMID 31426593, 2019). "We were unable to detect a gross change in total GAPDH protein levels during bacterial infection or flg22 elicited immune responses using anti-GAPDH western blotting." (PMID 25918875, 2015). "GAPDH is a SS surface protein and mediates cell adhesion and plays an important role in bacterial infection and invasion." (PMID 22514606, 2012). "As shown here, the GBS GAPDH induced host IL-10 production detected early after bacterial infection." (PMID 22114550, 2011). "In addition, we also detected the active LC3B in treated cell lysate and the ratio of LC3B II/GAPDH were increased, conforming that autophagic cell death is activated in response to bacterial infection." (PMID 33643911, 2020). "Therapeutic action on the glycolytic or virulence-associated functions of GAPDH represents an attractive route to help curb bacterial infections, while it depends on the availability of specific drugs that can distinguish human GAPDH from the targeted pathogen." (PMID 28443070, 2017). "We have previously shown that in adult mice GBS glycolytic enzyme glyceraldehyde-3-phosphate dehydrogenase (GAPDH) is an extracellular virulence factor that induces production of the immunosuppressive cytokine interleukin-10 (IL-10) by the host early upon bacterial infection." (PMID 22114550, 2011). "The instability of GAPDH has been reported in numerous other systems, including different developmental stages of Atlantic halibut, embryonic development in zebra fish, virus-infected salmon, and different tissue types after bacterial infection in Japanese flounder." (PMID 28182746, 2017). "In the context of bacterial infection, the head RPS18 and GAPDH genes of Apis mellifera L. (Hymenoptera: Apidae) are able to express stably." (PMID 40266757, 2025).
neurological diseases (10 papers, 2017 to 2025). "Although there is no currently known pathology entirely attributed to zinc-mediated GAPDH inhibition, some neurological diseases have been associated with impaired GAPDH function." (PMID 33946782, 2021). "Although there is no data about a pathology wholly associated with the enzyme’s damage or deficiency, many neurological diseases are reported to partially implicate impaired, aggregating GAPDH or tumors, strongly depending on the energy supply promoted by this enzyme through the Warburg effect." (PMID 32370188, 2020). "This nuclear GAPDH cascade has been reportedly activated in more than one genetic cell and animal models for neurological disorders." (PMID 40903341, 2025). "In summary, these findings provide a new insight into the role of piceatannol interaction with GAPDH and propose a potential therapeutic strategy for some neurological disorders related to GAPDH aggregation." (PMID 29298351, 2018). "New studies suggested that in neurological diseases, housekeeping proteins such as β-actin and GAPDH may be changed after injury or in neuropathological states." (PMID 39139639, 2024). "Therefore, targeting specific sites on the GAPDH molecule may be useful for increasing the viability of cells subjected to proteotoxic factors, such as misfolded proteins in neurological diseases." (PMID 32370188, 2020). "This change may be prompted due to GAPDH, which, in addition to its role in glycolysis, is a multifunctional protein involved in oxidative and nitrosative stress in the brain, being related to neurological disorders." (PMID 30678170, 2019).
adenocarcinoma (7 papers, 2007 to 2022). A common cancer characterized by the presence of malignant glandular cells. "Strikingly, high expression of SLC2A1, encoding the glucose transporter GLUT1, and the glycolytic genes GAPDH and PGK1, were associated with strongly reduced OS, particularly in the adenocarcinoma subtype, consistent with the prognostic value of FDG-PET in LuAd." (PMID 31032816, 2019). "Similarly, in adenocarcinomas of the colon, the expression of RPLP0, RPS14 and GAPDH varied between primary tumors and corresponding resection margins." (PMID 17640361, 2007). "Notably, 4 of the glucose metabolism-related genes, GPI, G6PD, PKM2, and GAPDH and 5 of the cell cycle-related genes, ANLN, PTTG1, CIT, KPNA2, and CDC25A, were significantly down-regulated in EGFR m+ adenocarcinomas, and showed a substantial correlation with SUVmax." (PMID 28422979, 2017).
metabolic disorders (4 papers, 2014 to 2025). "The dysregulation of GAPDH function by oxPTMs has been associated with various human pathologies, including neurodegeneration and metabolic disorders." (PMID 33339386, 2020). "Finally, we will discuss the different human pathologies (e.g., neurodegeneration and metabolic disorders) associated with the oxidation-induced dysregulation of GAPDH." (PMID 33339386, 2020). "Dysregulated GAPDH function is also implicated in metabolic disorders, particularly diabetes." (PMID 33339386, 2020). "This section briefly summarizes the roles GAPDH plays in neurodegeneration and metabolic disorders, as well as therapeutic compounds that target redox-modified GAPDH." (PMID 33339386, 2020). "Human pathologies associated with the oxidation-induced dysregulation of GAPDH are also discussed, featuring the importance of the redox regulation of GAPDH in neurodegeneration and metabolic disorders." (PMID 33339386, 2020). "It is possible that the increase of GAPDH expression in our experimental model is due to a metabolic disorder Dex-induced." (PMID 25365174, 2014). "The covalent modification of TG2 substrates such as glyceraldehyde-3-phosphate dehydrogenase (GAPDH), alpha-ketoglutarate dehydrogenase, phosphoglycerate dehydrogenase, and fatty acid synthase, which are involved in energy metabolism, could account for the role of TG2 in metabolic diseases." (PMID 24778599, 2014).
colon (2 papers, 2009 to 2021). "Thirteen types of exosomes with different expression status in gastrointestinal tumors were included, and quantitative analysis was based on different reference genes (GAPDH, 18S rRNA, Cel-miR-39 or U6); and therefore, the heterogeneity was generated in the pooled effects." (PMID 33578545, 2021).
infectious disease (2 papers, 2019 to 2024). A disorder directly resulting from the presence and activity of a microbial, viral, or parasitic agent in humans. "However, parasite HSP90, GAPDH and enolase have been investigated as vaccine candidates of diverse infectious diseases, as these proteins have regions that evolutionarily diverged." (PMID 39529575, 2024). "Both synthetic ADP analogs and natural products have been established as antimicrobial agents targeting GAPDH, which has paved the way for their development as pharmaceutical lead compounds in the quest for new therapies against infectious diseases." (PMID 30863383, 2019).
GAPDH also shares sentences with these, for which no sentence is quoted: Parkinson’s (6 papers); adenoma (4); multiple myeloma (4); anemia (3); chronic obstructive pulmonary disease (3); Behçet's disease (2); breast (2); breast fibroadenoma (2); cardiovascular diseases (2); chronic lymphoid leukemia (2); Cirrhosis (2); cutaneous melanoma (2); diffuse large B-cell lymphoma (2); head and neck squamous cell carcinoma (2); Hepatic steatosis (2); insomnia (2); kidney cancer (2); kidney damage (2); mental disorder (2); nematode infections (2); nephropathy (2); neuromyelitis optica (2); Oral squamous cell carcinoma (2); renal cell carcinoma (2); scoliosis (2); tuberculosis (2); viral diseases (2); acute lung injury (1); acute myocardial infarction (1); Adenovirus infection (1).
A further 111 diseases each share a sentence with GAPDH in 1 paper.